IDH1 (isocitrate dehydrogenase (NADP(+)) 1)
Diseases named in the same sentence as IDH1 in open-access papers (continued):
Sharing a sentence is not in itself a finding about the gene and the disease.
brain cancer (22 papers, 2013 to 2025). A primary or metastatic malignant neoplasm affecting the brain. "Both, MGMT promoter methylation and IDH1 mutations are associated with a better overall survival of patients with primary brain cancers." (PMID 38835368, 2024). "Cancer distribution shows that mutated IDH1 is mainly found in brain cancer, in particular within LGG and only to a low extent in medulloblastoma." (PMID 30675185, 2019). "Recently, it was shown that NAMPT inhibitors lead to vulnerability in IDH1 mutated brain cancer cells." (PMID 31888244, 2019). "Other metabolic alterations include the production of the onco-metabolite 2-hydroxyglutarate (2-HG) as a result of a point mutation in the isocitrate dehydrogenase 1/2 (IDH1/2) gene, strongly associated with a discrete subset of brain cancers (IDH-mutant gliomas)." (PMID 37999235, 2023). "Mutations in IDH1 led to hypermethylation of the F3 promoter of the tissue factor gene leading to decreased expression and may explain the decreased risk of VTE in primary brain cancer patients with mutant IDH1." (PMID 32707653, 2020). "The novel PTEN-independent mode of mTORC1/2 activation via mutated IDH/2HG/KDM4A/DEPTOR revealed here may provide an additional molecular explanation for the oncogenic activity of IDH1/2 mutation in brain cancer." (PMID 27624942, 2016). "Furthermore, we found the mutational status of the histone methyltransferase SET-domain containing-2 (SETD-2) as a significant contributor in kidney, smoking in bladder and lung, and isocitrate dehydrogenase 1 (IDH1) mutational status in brain cancers." (PMID 27966532, 2016). "Overall TET2 and IDH1/2 mutations are being mainly described in haematopoietic and brain cancers, but recently, it was shown that 5-hydroxymethylcytosine depletion was detected in those and other cancers such as squamous cell lung cancer, in the absence of TET2 and IDH mutations." (PMID 23998913, 2013). "While age would increase the likelihood of any mutation arising by chance alone, our results suggest that age might disproportionately favour the occurrence of mutations other than IDH1 p.R132H in these brain cancers, or that this mutation confers a greater selective advantage in younger people." (PMID 30412573, 2018). "R132H IDH1 is an important therapeutic target for a variety of brain cancers, yet drug leads and radiotracers which selectively bind only to the mutant over the wild type are so far lacking." (PMID 40569935, 2025). "We also identify negative associations (odds ratio < 1) between mutational signatures and driver mutations, and here we examine the role of aging and cigarette smoke mutagenesis in the generation of driver mutations in IDH1 and KRAS in brain cancers and lung adenocarcinomas respectively." (PMID 30412573, 2018). "Most IDH1 mutant brain cancers fail to express MGMT protein, largely due to promoter methylation, which may explain better therapeutic responses in patients positive for IDH1 mutations." (PMID 28346397, 2017). "Importantly, the loss of 5-hmC in brain cancer did not exhibit any correlation with IDH1 or IDH2 mutations." (PMID 29290954, 2017). "Mutations in key metabolic enzymes Isocitrate dehydrogenase 1 and 2 (IDH1 and IDH2) are defining features of primary brain cancers that include low-grade gliomas and secondary GBM." (PMID 33137926, 2020).
epilepsy (22 papers, 2013 to 2025). A brain disorder characterized by episodes of abnormally increased neuronal discharge resulting in transient episodes of sensory or motor neurological dysfunction, or psychic dysfunction. "The epileptogenic action of the d-2-HG oncometabolite and its ability to activate the mTOR pathway open up the potential use of mTOR inhibitors as rapamycin, everolimus, and temserolimus for patients with IDH1 mutated tumors and drug refractory epilepsy." (PMID 37071297, 2023). "Overall, these results suggest the potential use of KDM5C as a molecular stratification factor in GBM, with a particular attention for patients with epilepsy and IDH1/2 mutations." (PMID 36142158, 2022). "The results showed that isocitrate dehydrogenase 1 (IDH1) mutation was significantly correlated with the incidence of perioperative epilepsy." (PMID 34539550, 2021). "The aim of this study was to investigate the potential correlation between tumor-associated epilepsy and IDH1 mutations in a Chinese population with LGGs." (PMID 24324372, 2013). "The aim of this study was to investigate the potential correlation between tumor-associated epilepsy and IDH1 mutation in a Chinese population with LGGs." (PMID 24324372, 2013). "Some studies have also linked glioma-associated epilepsy with IDH1 mutation." (PMID 30621209, 2019). "Also, IDH1 mutation was linked to the risk of tumor-associated epilepsy and seizure prognosis." (PMID 30621209, 2019). "A seizure is often the precipitating event for diagnosis, and epilepsy is more prevalent in IDH1 mutant tumors, which have a better prognosis." (PMID 37071297, 2023). "Supporting that possibility, we did not see a consistent histone acetylation signature among a panel of IDH1 wildtype, IDH1 mutant and epilepsy surgical samples." (PMID 37528157, 2023). "Of the 23 patients without epilepsies, 14 cases (60.9%) had IDH1 mutation, whereas 32 cases were found to have IDH1 mutation among the 37 epileptic patients (86.5%) (P = 0.023, chi-square test)." (PMID 24324372, 2013). "A subgroup analysis showed that IDH1 was significantly correlated with the incidence of preoperative epilepsy, but not with intraoperative and postoperative epilepsy." (PMID 34539550, 2021). "Noteworthy, the two KDM5C subgroups showed significant changes in NANOG expression in the subset of patients without epilepsy or with the wild-type IDH1/2 genotype or with MGMT methylation, while significant OCT4 change was found in the subset of patients with the wild-type IDH1/2 genotype." (PMID 36142158, 2022).
osteosarcoma (20 papers, 2010 to 2025). A usually aggressive malignant bone-forming mesenchymal neoplasm, predominantly affecting adolescents and young adults. "A similar situation was found in osteosarcoma samples, where among seven tumors, two chondroblastic osteosarcomas were also IDH1 mutation-positive." (PMID 38248076, 2024). "In osteosarcoma patients (n = 7), two samples were found to be positive for the IDH1 mutation; both cases were diagnosed as a chondroblastic variant of osteosarcoma." (PMID 38248076, 2024). "The detection of IDH1 mutations in chordoma (2/15) and osteosarcoma (2/7) suggested the need for a revised diagnosis." (PMID 38248076, 2024). "Upregulation of IDH1 has been found in osteosarcoma development and is associated with poor overall survival." (PMID 36601689, 2023). "In the near future, we expect to analyze IDH1/2 mutations using many more Japanese or Chinese osteosarcoma patients." (PMID 24403254, 2013). "Taken together, these results show that MsMab-1 can be anticipated for use in immunohistochemical determination of IDH1/2 mutation-bearing osteosarcoma." (PMID 24403254, 2013). "MsMab-1 stained nine of 32 (28.1%) osteosarcomas, indicating that MsMab-1 is extremely useful for the immunohistochemical detection of mutated IDH1/2 in osteosarcomas." (PMID 24403254, 2013). "In the near future, IDH1/2 mutations will be acknowledged as useful diagnostic markers for osteosarcomas." (PMID 24403254, 2013). "Since IDH1/2 mutations are uncharacteristic for chordoma and osteosarcoma, these results may request a revision of the diagnosis." (PMID 38248076, 2024). "To explore whether SIX4‐mediated osteosarcoma metastasis is associated with upregulation of IDH1, we examined the expression of IDH1 in SIX4 overexpression and knockdown cells." (PMID 36601689, 2023). "Finally, we performed immunohistochemistry against osteosarcoma tissue microarray using MsMab-1 mAb to investigate the expression of mutated IDH1/2." (PMID 24403254, 2013). "In that report, osteosarcoma samples from 222 patients, 19 osteosarcoma cell lines, and one chordoma cell line were tested for IDH1 mutations using the high-throughput MassARRAY platform: 64.4% (143 samples) of these were also analyzed for IDH2 mutations, including all chondroblastic osteosarcomas." (PMID 24403254, 2013). "Moreover, high IDH1 level was also associated with poor prognosis of osteosarcoma patients." (PMID 33468990, 2021). "Moreover, AHA1 and IDH1 could serve as effective diagnostic and prognostic biomarkers for osteosarcoma patients." (PMID 33468990, 2021). "Altogether, upregulation of SIX4 altered glycolysis and transcriptionally activates IDH1 in osteosarcoma." (PMID 36601689, 2023). "SIX4 promotes progression of osteosarcoma via upregulating isocitrate dehydrogenase 1 (IDH1), which provides novel prognostic biomarkers and promising therapeutic targets for osteosarcoma patients." (PMID 36601689, 2023). "Mutations in IDH1 can be used to differentiate DDCS from undifferentiated pleomorphic sarcoma, fibrosarcoma, and osteosarcoma." (PMID 37568740, 2023). "Taken together, these results demonstrated that IDH1 knockdown significantly suppressed the SIX4‐driven metastasis of osteosarcoma." (PMID 36601689, 2023). "In conclusion, our study found that SIX4 promotes progression of osteosarcoma via upregulating IDH1 and metabolic reprogramming, which provides novel prognostic biomarkers and promising therapeutic targets for osteosarcoma patients." (PMID 36601689, 2023). "In this study, we demonstrated that overexpression of SIX4 promoted osteosarcoma metastasis by changing glycolysis and upregulating isocitrate dehydrogenase 1(IDH1) expression." (PMID 36601689, 2023). "In conclusion, this study shows AHA1 promotes the growth and metastasis of osteosarcoma by upregulating IDH1 and metabolic activity." (PMID 33468990, 2021). "And IDH1 knockdown also increased the sensitivity to both 17AAG and Ganetespib in osteosarcoma cells with AHA1 knockdown." (PMID 33468990, 2021).
osteosarcoma (continued). "Compared with adjacent normal tissues, the mRNA level of IDH1 was significantly upregulated in osteosarcoma tissues." (PMID 33468990, 2021). "In the future, more osteosarcoma tissue samples should be studied to confirm the potential value of AHA1, IDH1, and the combination of them in the diagnosis and prognosis prediction of osteosarcoma patients." (PMID 33468990, 2021). "Further studies suggested that AHA1 promoted the growth and metastasis of osteosarcoma both in vitro and in vivo by upregulating IDH1 and metabolic activity." (PMID 33468990, 2021). "Overexpression of IDH1 partially reversed the suppressive effects of AHA1 knockdown on osteosarcoma cells." (PMID 33468990, 2021). "Surprisingly, a similar mechanism associated with the induction of apoptotic death was mediated by upregulation of IDH1 in osteosarcoma cell lines." (PMID 33321940, 2020). "This inhibitory effect was analyzed further in an osteosarcoma cell line with the inducible IDH1 gene." (PMID 26161668, 2015). "For this study, we analyzed IDH1 and IDH2 mutations using 12 osteosarcoma specimens with direct DNA sequencing." (PMID 24403254, 2013). "The combination of immunohistochemistry using our developed anti-mutated IDH1/2 mAbs and serum measurement of an oncometabolite 2-HG is expected to improve osteosarcoma patient selection for IDH1/2-targeted therapy." (PMID 24403254, 2013). "Expression of IDH1 is specifically detected in the cytoplasm of both osteosarcoma cell lines U2OS and MG63." (PMID 20459648, 2010). "Upregulation of IDH1 was further validated in osteosarcoma patients with undesirable outcomes." (PMID 36601689, 2023). "Consistently, AHA1 overexpression dramatically increased IDH1 in osteosarcoma cells." (PMID 33468990, 2021). "Notably, the positive co-expression relationship between AHA1 and IDH1 was further confirmed in osteosarcoma tissues." (PMID 33468990, 2021). "This study demonstrates that AHA1 positively regulates IDH1 and metabolic activity to promote osteosarcoma growth and metastasis, which provides novel prognostic biomarkers and promising therapeutic targets for osteosarcoma patients." (PMID 33468990, 2021). "Notably, there is a positive co-expression relationship between AHA1 and IDH1 in osteosarcoma tissues." (PMID 33468990, 2021). "Moreover, Hsp90-AHA1 complex interacts with IDH1 and regulates IDH1 level to affect the metabolic activity of osteosarcoma cells." (PMID 33468990, 2021). "In conclusion, these results indicate that AHA1 and IDH1 might have oncogenic functions and potential values in osteosarcoma prognosis prediction." (PMID 33468990, 2021). "On the other hand, IDH1 R132C inhibited expression of the ALPL gene in association with an increase in the repressive mark (H3K9me3), and subsequently inhibited the osteogenic properties of hMSCs and human osteosarcoma cells." (PMID 26161668, 2015). "Although osteosarcomas are the most frequent primary malignant bone tumors, no patients with IDH1 mutations have been described in previous and current studies on osteosarcomas." (PMID 26161668, 2015). "Osteogenic properties are one of most important diagnostic features of osteosarcomas, and, therefore, the inhibitory effect of IDH1 R132C on osteogenic differentiation may interfere tumor cells to be diagnosed as osteosarcoma." (PMID 26161668, 2015).
osteosarcoma (continued). "IDH1/2 mutation analysis against osteosarcoma has been performed in several studies, but no IDH1/2 mutation has been reported yet." (PMID 24403254, 2013). "Although IDH1/2 mutation analysis against osteosarcoma has been performed in several studies, no IDH1/2 mutation has been reported." (PMID 24403254, 2013). "IDH1 expresses higher in low Rosen grade osteosarcoma vs. high Rosen grade osteosarcoma." (PMID 20459648, 2010). "Interestingly, while some studies have investigated IDH1/2 mutations in osteosarcoma, only one study reported the novel detection of the IDH2 R172S mutation in three out of 12 osteosarcoma patients (25 %) using direct DNA sequencing." (PMID 40288045, 2025). "Furthermore, the IDH1 protein level was positively correlated with AHA1 in osteosarcoma." (PMID 33468990, 2021). "Notably, Kaplan–Meier analysis revealed that high IDH1 protein level was associated with poor overall survival (p = 0.0145) and disease-free survival (p = 0.0828) (109 patients), which suggests osteosarcoma patients with lower IDH1 protein expression exhibited better prognosis." (PMID 33468990, 2021). "Since osteogenic properties are an indispensable feature for the diagnosis of osteosarcoma, the inhibitory effects of IDH1 R132C on osteogenic properties may contribute to the lack of osteosarcomas with the IDH1 R132C mutation." (PMID 26161668, 2015). "However, it may, from the theoretical point of view, still be valuable to study the role of IDH1 in osteosarcoma." (PMID 20459648, 2010). "Collectively, these data indicate that restoration of IDH1 expression partially reverses the suppressive effects of AHA1 knockdown on the growth and migration of osteosarcoma cells." (PMID 33468990, 2021). "Furthermore, we found IDH1 knockdown enhanced the effect of AHA1 knockdown on the growth and migration of osteosarcoma cells." (PMID 33468990, 2021). "Furthermore, osteosarcoma patients with lower protein expression of both AHA1 and IDH1 exhibited better prognosis, even though the difference of disease-free survival were not statistically significant due to the inadequate number of cases." (PMID 33468990, 2021). "And IDH1 overexpression could partially reverse the effect of AHA1 knockdown on cell growth and migration of osteosarcoma." (PMID 33468990, 2021). "Across all Ewing and osteosarcoma cell lines eleven genes were found to be either significantly (P < 0.05, Bonferroni correction) repressed (KIF20A, IDH1, SCD, GPSM2, EIF2AK4, HIBCH) or induced (STK19, DNAJC24, MTG2, FAM175B, CYB5D1) following non DNA-damaging XI-006 treatment (0.5 μM)." (PMID 26095524, 2015). "But, there is no study on the expression of IDH1 in osteosarcoma." (PMID 20459648, 2010).